ENSG00000212586
Synonyms: LOC124900223
Gene: Small nucleolar RNA gene on chromosome 6 (38,822,307 to 38,822,404, reverse strand). Ensembl gene ENSG00000212586.
Gene Ontology:
Biological process: RNA processing
Cellular component: nucleolus
Homologues: Orthologues: mouse Gm25791 (79% identical), mouse Gm26236 (77% identical). Paralogues in human: SNORA8 (89% identical).